MMP9 (matrix metallopeptidase 9)
Diseases named in the same sentence as MMP9 in open-access papers (continued):
Sharing a sentence is not in itself a finding about the gene and the disease.
Sepsis (continued). "It has been demonstrated that MMP-9 secretion from leukocytes significantly increases during inflammation and sepsis." (PMID 29734352, 2018). "Several studies attempting to elucidate the molecular mechanisms of hyperglycemia and sepsis have revealed elevated levels of Matrix-Metalloproteinase-9 (MMP-9)." (PMID 27110221, 2016). "The rise in MMP-9 levels in patients with severe sepsis or septic shock has been described to occur very early in the disease process." (PMID 27110221, 2016). "Matrix-Metalloproteinase 9 (MMP-9) has been shown to be elevated in acute stress hyperglycemia, chronic hyperglycemia, and in patient with sepsis." (PMID 27110221, 2016). "Of note, serum SAA1, HAMP1, and MMP9 levels are elevated during human sepsis and have been investigated as prognostic biomarkers (66, –, 68)." (PMID 27303721, 2016). "Another alternative that has shown to decrease circulating levels of MMP-9 and improve survival in the setting of sepsis is the use of hemoperfusion using polymixin B immobilized on fibers (PMX-F)." (PMID 27110221, 2016). "The objectives of this study were to investigate the utility of MMP9, TIMP1, mrProANP, and A-FaBP as diagnostic biomarkers in pediatric patients with severe sepsis and septic shock." (PMID 27089280, 2016). "MMP-9, TIMP-1levels, and MMP-9/TIMP-1 ratio have previously been studied as biomarkers in adult severe sepsis and septic shock." (PMID 27089280, 2016). "Since then, various studies have corroborated the increase of MMP-9 levels in patients with severe sepsis or septic shock and their poor outcomes." (PMID 27110221, 2016). "In one of our previous study in which we described the natural history of circulatory biomarker activity in the most proximal phases of severe sepsis and septic shock we also noted that MMP-9 levels peaked early (6 h) after presentation." (PMID 27110221, 2016). "In this case, the prophylactic administration of CMT in the setting of sepsis has shown to effectively decrease MMP-9 levels and improve survival." (PMID 27110221, 2016). "In patients with sepsis, high levels of MMP-8 have been associated with increased ICU and 28-day mortality, whereas lower levels of MMP-9 have been linked to better survival." (PMID 25945788, 2015). "Only in 10 out of 20 patients with severe sepsis on the intensive care unit, activated MMP-9 was found." (PMID 24675764, 2014). "The mRNA and protein levels of MMP-9 in the sepsis group and the Sc were higher than those in the healthy group, and this difference was statistically significant (P<0.05)." (PMID 24913772, 2014). "Detection of MMP-9 activity in the lung tissue using gelatin zymography revealed that the protein levels of MMP-9 in the siRNA group decreased in comparison with the sepsis and the Sc groups, and the difference at 6 h was statistically significant (P<0.05)." (PMID 24913772, 2014). "It is reported that MMP-9 and gelatinase activity increased significantly after sepsis, and TIMP-1, an MMP-9 inhibitor, blocked these activities, as well as the ensuing septic shock." (PMID 25407832, 2014). "Sepsis associated with increased MMP-8 and decreased MMP-9 levels in multivariate analysis (p < 0.0002)." (PMID 24833564, 2014). "High MMP-8 and low MMP-9, which correlated with plasma CRP levels, were associated with sepsis, in addition to high fibrinogen levels and neutrophils counts." (PMID 24833564, 2014). "This is the first longitudinal study reporting the levels of MMP-2, MMP-8 and MMP-9 in the patients with severe sepsis." (PMID 20356362, 2010). "• Levels of MMP-2 and MMP-8 were up-regulated in severe sepsis in comparison with healthy controls, both in skin blister fluid and in the serum, whereas MMP-9 levels were lower in serum in sepsis from the fourth day onwards." (PMID 20356362, 2010). "We measured the MMP-2, MMP-8 and MMP-9 levels during human severe sepsis and after recovery in serum and locally in skin using the suction blister method." (PMID 20356362, 2010).
Sepsis (continued). "We found low MMP-9 levels also in skin blister fluid samples of patients with severe sepsis in comparison with the controls." (PMID 20356362, 2010). "Taken together, it seems that the MMP-9 levels are elevated at the very early phase of severe sepsis, but the levels drop later on." (PMID 20356362, 2010). "Compared to the controls MMP-9 levels were lower in sepsis from the fourth day on in serum and both the first and fifth day in skin blister fluid." (PMID 20356362, 2010). "An association was found between MMP-9, MMP-10, TIMP-1, and MMP-9/TIMP-1 ratios and parameters of sepsis severity, assessed by the SOFA score, the APACHE-II score, lactic acid, platelet count, and markers of coagulopathy." (PMID 19799791, 2009). "Next, the ROC curves show that the ITGAM, CXCR2, and FCGR3B expression levels provide high accuracy for classifying the Sepsis and Control group (AUC > 0.9); MMP9, MPO, and CTSG expression levels exhibit moderate accuracy for this classification (0.7 < AUC < 0.9)." (PMID 41259376, 2025). "Furthermore, MMP9 levels in septic shock patients were significantly higher than those in simple sepsis patients, indicating that MMP9 protein levels are sepsis specific and correlated with disease severity." (PMID 41306770, 2025). "Current evidence demonstrates that sepsis-induced activation of the AKT signaling pathway leads to upregulation of downstream effectors including MMP-9 and COX-2, accompanied by elevated inflammatory cytokine levels, ultimately contributing to intestinal barrier dysfunction and multi-organ injury." (PMID 40885907, 2025). "In conclusion, this study revealed the potential molecular mechanisms of key common genes with LTF and MMP9 in pediatric sepsis and relapsed B-ALL, which could provide novel insights for the clinical diagnosis of these two diseases." (PMID 41007866, 2025). "Differential analysis identified 6 proteins that were significantly upregulated in sepsis serum samples, including MMP9, lipocalin-2 (LCN2), serum amyloid A1 (SAA1), serum amyloid A2 (SAA2), paired-like homeobox 2B (PHOX2B), and lactoferrin (LTF) (|log2FC| > 1, P < 0.05)." (PMID 41306770, 2025). "Moreover, MMP9 showed strong performance in distinguishing septic shock from simple sepsis (AUC = 0.7525)." (PMID 41306770, 2025). "MMP9 had been identified as an immune related gene in severe burns and sepsis, and during septic progression, endotoxin-mediated leukocyte hyperactivation drives the concurrent release of proinflammatory mediators and concomitant MMP9 overexpression." (PMID 41007866, 2025). "This review links molecules (TNF-α, CCL2, ROS, VEGF, MMP-9, and NO) secreted by macrophages under inflammatory conditions to endothelial cell dysfunction (adhesion, permeability, and coagulability), refining the pathophysiologic mechanisms of sepsis." (PMID 39199368, 2024). "Previous studies have found that MMP-9 responds to various inflammatory mediators and is released rapidly in the body circulation, and MMP9 deficiency can prevent the death of LPS-induced sepsis models by alleviating harmful systemic inflammatory responses generated by the host." (PMID 38029239, 2023). "MMP-2/MMP-9 has been correlated with the severity of sepsis." (PMID 37504075, 2023). "Moreover, the interaction between MMP9 and other key proteins in sepsis formation has also been poorly explored." (PMID 38029239, 2023). "MMP9 was highly expressed in the veins of mice with sepsis and DVT." (PMID 38029239, 2023). "Recently, it has been suggested that MMP-9 blocking could be exploited as a possible therapeutic approach for sepsis." (PMID 37622890, 2023). "We speculate that MMP9 may be an important link in the interaction between sepsis and VTE, and an important molecule that worsens the disease and amplifies the clinical effect when sepsis and VTE are comorbidities." (PMID 38029239, 2023). "Here, MMP-9 is studied as one of the biomarkers that can be used for the early detection of sepsis." (PMID 37622890, 2023).
Sepsis (continued). "In this study, we investigated the use of MMP-9 as a biomarker for sepsis." (PMID 37622890, 2023). "The prognostic role of TIMP1 and MMP9 during sepsis was confirmed by another study." (PMID 37817235, 2023). "Therefore, in order to evaluate the role and influence of in vitro sepsis on vascular endothelium, we next examined the expression level of MMP9 protein after LPS stimulation of HUVECs." (PMID 38029239, 2023). "In addition, MMP8 and MMP9 inhibitors have been shown to have significant effects on improving BBB permeability in mice after sepsis." (PMID 36445634, 2023). "ascribed elevated MMP9 as well as ARG1 expression in whole blood during sepsis to MDSCs, which may also have been present in our CD15 cell fraction." (PMID 35844509, 2022). "The AST could affect the TNF, PI3K, and MAPK pathway cascade responses centred on IκBα and NF-κB, attenuate the expression of IL-6 and MMP9, and interfere with the inflammatory response during sepsis." (PMID 35399630, 2022). "The results suggested that the expressions of LCK and CCL5 were significantly higher in normal samples than in samples from patients with sepsis, while the expressions of ITGAM and MMP9 were significantly lower in normal samples than in samples from patients with sepsis in the GSE57065 dataset." (PMID 35184762, 2022). "In addition, MMP9 has high accuracy in the diagnosis of sepsis, and the result of ROC curve analyses showed the area under the curve of MMP9 was 0.967, indicating that MMP9 plays an important role in the pathogenesis of sepsis." (PMID 35190763, 2022). "In humans, expression of MMP-9 during sepsis and endotoxemia is known for a longer time." (PMID 33488296, 2021). "Moreover, the expression of MMP-9 was positively correlated with the severity of sepsis as measured by Acute Physiology, Age, and Chronic Health Evaluation III (APACHE III) scores." (PMID 33431821, 2021). "Therefore, future investigations are warranted to safely include Mmp9 into viable clinical treatments for sepsis-related inflammation." (PMID 34684425, 2021). "Based on the results of this primary project and so far only 6 horses classified as sepsis-positive, MMP-9 may be useful to evaluate the severity of endotoxemia and may have prognostic value for equine colic." (PMID 33488296, 2021). "Notably, local suppression of MMP-9 in the lung led to a significant increase in sepsis-induced mortality." (PMID 33628393, 2021). "We also performed a limited clinical study to determine if MMP-9 is a biomarker of sepsis." (PMID 33431821, 2021). "The hub genes for MMP-9 were significantly related to the prognosis of sepsis patients." (PMID 33488296, 2021). "Increased Il6 and MMP9 levels are well described in inflammation and during sepsis." (PMID 33178198, 2020). "Furthermore, MMP-9 is also able to cleave surface-associated CD40L on activated platelets, thereby controlling pulmonary accumulation of neutrophils in sepsis." (PMID 32645949, 2020). "We also found a higher expression of ELANE and MMP9 in sepsis." (PMID 31817302, 2019). "The contradictory results observed with MMP9 in severe sepsis may be due to differences in the sample population, sampling time, MMP9 estimation techniques, or clinical endpoints." (PMID 31817302, 2019). "However, many studies correlate increased MMP9 with increased mortality by aggravating severe sepsis." (PMID 31817302, 2019). "The serum levels of MMP-9 are elevated in patients with both sepsis and septic animal models." (PMID 31213027, 2019). "Interestingly, in severe sepsis, the expression levels of MMP-9, TIMP-1, and TIMP-2 are also significantly elevated." (PMID 31671729, 2019). "It had been indicated that inhibition of MMP-9 and MMP-2 levels could effectively reduce the level of inflammatory cytokines in the brain and improve cognitive impairment caused by sepsis." (PMID 31213027, 2019).
Sepsis (continued). "Therefore, several reports have shown that MMP-9 plays an essential role in the pathogenesis of inflammation diseases, such as multiple sclerosis, arthritis, ischemic stroke, and sepsis." (PMID 31213027, 2019). "The results obtained were consistent with studies that suggest a protective role of MMP9 in sepsis." (PMID 31817302, 2019). "We speculated that GAPDH, MAPK8, PIK3CB, and MMP9 may play important roles in the ARDS-specific neutrophil phenotype distinct from sepsis." (PMID 31531373, 2019). "However, another clinical study in patients who suffer from septic shock demonstrated that higher MMP-9 level was found in patients who suffocated from severe sepsis compared to the survivors and healthy controls." (PMID 30142934, 2018). "A negative correlation between PCT and MMP-9 is expected given the association of higher PCT levels with more severe forms of sepsis." (PMID 29861795, 2018). "MMP-9, TIMP-2 and TIMP-1 have been shown to be elevated in patients with severe sepsis and septic shock as well as in animal models of endotoxemia, while MMP-1, MMP-8 and MMP-13 have also been associated with sepsis." (PMID 30466423, 2018). "Our findings suggest that platelet expression of MMP-9 is also upregulated in sepsis." (PMID 29734352, 2018). "Our results also suggest that major abdominal surgery, independent of sepsis, is associated with lower MMP-9 levels." (PMID 29861795, 2018). "Future studies could possibly provide more insight into MMP-9 and TIMP-1's role in the pathophysiology of the sepsis-associated organ dysfunction." (PMID 29861795, 2018). "We report for the first time that CB2 regulates MMP-9 levels in a sepsis model, and further investigation is required to determine whether this accounts for differences in neutrophil mobilisation." (PMID 28852269, 2017). "Taken together, these findings suggested that WK2-16 with HDAC8 inhibition could abrogate MMP-9 and IL-6 production, possibly providing a novel therapeutic strategy of sepsis and systemic inflammation." (PMID 28661460, 2017). "High MMP-9 levels have been identified in patients in severe sepsis or septic shock." (PMID 27110221, 2016). "However, the more clinical relevant question is to determine the appropriate treatment window in which CMTs can be administered in order to decrease MMP-9 levels, improve survival, and decrease the sequela of sepsis (i.e. ARDS; liver failure)." (PMID 27110221, 2016). "The role of MMP-9 role in sepsis may be related to its function in the cleavage of collagen in the basement membrane, thereby enabling leukocytes and lymphocytes to enter and leave the peripheral circulation." (PMID 27089280, 2016). "In sepsis, altered levels of MMP-8, MMP-9, and TIMP-1 have been associated with adverse outcome." (PMID 25945788, 2015). "A novel finding of the current study was that TIMP-1/MMP-9 ratio during the first week could be used as a biomarker of sepsis outcome according to the results of ROC curve analysis." (PMID 24727739, 2014). "Plasma MMP-9 levels were lower in septic patients compared to those of the controls, a fact to consider because decreased plasma MMP-9 levels were associated with sepsis in the multivariate logistic regression in our study." (PMID 24833564, 2014). "In fact, this might lead to a massive release of MMP-9, which in turn may contribute to the vascular leakage observed during sepsis." (PMID 24458309, 2014). "Previously elevated MMP-9 levels have been reported within 24 hours from severe sepsis diagnosis." (PMID 20356362, 2010). "Therefore, besides the already known higher mortality rate in sepsis patients with increased lactic acid levels and SOFA score, our results suggest that alterations in the MMP-9/TIMP-1 ratio and MMP-10 levels are associated with the severity of sepsis." (PMID 19799791, 2009).
Sepsis (continued). "Additionally, MMP9 induced increased PD-1 expression on CD4+ T cells and reduced IL-2 and IFN-γ production upon anti-CD3/CD28 stimulation, confirming the association between MMP9 and CD4+ T cell exhaustion during sepsis." (PMID 41306770, 2025). "Since sepsis management relies on timely antibiotics and supportive care, a key direction is to determine whether MMP9-in-1 acts synergistically with standard-of-care antibiotics, potentially addressing both the pathogen burden and the resulting immunosuppression concurrently." (PMID 41306770, 2025). "However, current reports on whether MMP-9 can predict the mortality of sepsis patients are inconsistent, which may be attributed to the heterogeneity of disease severity and research methods employed across studies." (PMID 38029239, 2023). "In terms of mechanism, MMP9 may play an important role in promoting the formation of VTE in sepsis." (PMID 38029239, 2023). "Therefore, we studied the expression of MMP9 in mice with sepsis with DVT." (PMID 38029239, 2023). "Thus, we conclude that MMP-9 can be used as an effective biomarker for sepsis and could detect the disease at all stages, thus providing very useful information about the sepsis patient’s status." (PMID 37622890, 2023). "MMP9 (gelatinase B) plays a key role in normal physiology (e.g., in embryonic development, reproduction, cell migration, angiogenesis, neovascularization and bone development), as well as in pathologies, such as arthritis, sepsis, cancer metastasis, cardiovascular diseases and hemorrhage." (PMID 36009335, 2022). "Therefore, we speculated that MMP9 might relate to activation of NK cells and play a role in NK cells anergy in sepsis and trauma." (PMID 35615364, 2022). "Finally, we identified a four-gene signature, containing the hub genes LCK, CCL5, ITGAM, and MMP9, and established a model that could be used to diagnose patients with sepsis." (PMID 35184762, 2022). "Hence, further investigations are warranted to explore whether and how MMP-9 is involved in the pathophysiology of sepsis-induced ALI/ARDS." (PMID 33628393, 2021). "Therefore, this study is aimed at clarifying whether and how pulmonary knockdown of MMP-9 affected sepsis-induced acute lung injury as well as the release of sRAGE in a murine cecal ligation and puncture (CLP) model." (PMID 33628393, 2021). "Therefore, this study first clarified whether and how pulmonary knockdown of MMP-9 affected sepsis-induced acute lung injury as well as the release of sRAGE in a murine CLP model." (PMID 33628393, 2021). "We then investigated whether MMP-9 upregulation was involved in sepsis-induced lung injury." (PMID 33628393, 2021). "MMP-9-mediated sRAGE production may serve as a self-limiting mechanism to control and resolve excessive inflammation and oxidative stress in the lung during sepsis." (PMID 33628393, 2021). "Our data indicate that MMP-9-mediated sRAGE production may serve as a self-limiting mechanism to control and resolve excessive inflammation and oxidative stress in the lung during sepsis." (PMID 33628393, 2021). "The objectives of this study were to investigate, for the first time, MMP-9, TIMP-1, and the MMP-9/TIMP-1 ratio as diagnostic and prognostic biomarkers of sepsis after major abdominal surgery as well as the potential relationships between these biomarkers and sepsis-associated organ dysfunction." (PMID 29861795, 2018). "In addition, antagonizing the up-regulation of MMP-9 could serve as a potential treatment option in severe sepsis or septic shock patients." (PMID 27110221, 2016). "Our previous studies demonstrated a unique form of neutrophil matrix-metalloproteinase 9, covalently linked to haptoglobin (Hp-MMP 9) are stored in and released by neutrophils; and these complexes are present within the serum of cattle with acute, polymicrobial sepsis." (PMID 25358728, 2014).